TLR9 (toll like receptor 9)
Diseases named in the same sentence as TLR9 in open-access papers (continued):
Sharing a sentence is not in itself a finding about the gene and the disease.
pancreatic cancer (continued). "To conclude, our results demonstrate the TLR2 and TLR9-specific intrabody-mediated signaling pathway inhibition of autoregulatory inflammation inside cancer cells and their proliferation, resulting in the suppression of pancreatic tumor cell growth." (PMID 38390872, 2024). "To investigate the potential of TLR2 and TLR9 inhibition in pancreatic cancer cells and its efficacy in tumor cell death, we developed pCMV Myc NCAM1, pCMV Myc TLR2, and pCMV Myc TLR9 plasmids expressing NCAM1 intrabodies (control intrabodies) and TLR2- and TLR9-specific intrabodies." (PMID 38390872, 2024). "Targeting TLR-mediated inflammatory signaling and, particularly, TLR2 and TLR9 may therefore be beneficial for patients with pancreatic cancer." (PMID 38390872, 2024). "TLR2 and TLR9 expression was demonstrated to be upregulated in human PDACs, which was confirmed by our previous data and is listed in detail for human PDACs and established pancreatic cancer cell lines, including PANC-1 and BXPC-3." (PMID 38390872, 2024). "We performed proof-of-concept studies to investigate whether TLR2 and TLR9 intrabodies that we generated could inhibit pancreatic cancer cell growth, decrease inflammatory markers, and induce apoptosis." (PMID 38390872, 2024). "Subsequently, the stimulation of TLRs can actuate some adverse protumoral signaling pathways, such as TLR2, TLR4, and TLR9, which activate signaling pathways and anti-apoptotic Bcl-xL expression in terms of tumor cell activation and proliferation in pancreatic cancer." (PMID 33505964, 2020). "Similarly, expression of TLR9 has been found to correlate with the invasive and metastatic potential of pancreatic carcinoma." (PMID 28744288, 2017). "In the current study, we show that neither genetic deletion of TLR9 nor blockade of TLR7/9 using IRS 954 significantly altered the metabolic changes associated with pancreatic cancer cachexia." (PMID 26172047, 2015). "We found that TLR2 and TLR9, along with TLR4, play an important role in the growth of pancreatic cancer." (PMID 38390872, 2024). "We have shown that the upregulated cell surface expression of Toll-like Receptor (TLR) 2 and of TLR9 inside PDAC cells maintain chronic inflammatory responses, support chemotherapeutic resistance, and mediate tumor progression in human pancreatic cancer." (PMID 38390872, 2024). "Along with targeting cell surface TAAs, ER intrabodies targeting membrane proteins in intracellular compartments have also been developed, such as intrabodies against toll-like receptor 9 (TLR9), which diminishes the development of pancreatic tumor." (PMID 38213543, 2023). "To detect signaling pathways that may be involved in pancreatic cancer cell death through TLR2 and TLR9 intrabody-mediated intracellular inhibition, we performed a Western blot analysis of STAT3 phosphorylation changes in the treated cells." (PMID 38390872, 2024). "Interestingly, stimulation of TLR9 and in part TLR2 resulted in upregulated VEGF gene expression (BxPC-3) and particularly of PDGF in all three analyzed human pancreatic cancer cell lines." (PMID 27941651, 2016). "However, to our knowledge neither TLR7 nor TLR9 has been studied in the treatment of pancreatic cancer cachexia." (PMID 26172047, 2015). "More recently, we described in advanced stage pancreatic cancers overexpressed TLR2, TLR4, TLR7, and TLR9 predominantly in tumor cells rather than tumor-infiltrating immune cells, making TLR inhibition strategies in this tumor even more interesting." (PMID 38390872, 2024). "To dissect the effects of TLR activation, we treated two of the established pancreatic cancer cell lines (BxPC-3 and MIAPaCa-2) and one primary pancreatic cancer cell line (PaCaDD135) with TLR specific ligands (LTA for TLR2, LPS for TLR4, ODN for TLR9) and a non-specific ligand (HMGB1)." (PMID 27941651, 2016).
tuberculosis (17 papers, 2006 to 2025). A chronic, recurrent infection caused by the bacterium Mycobacterium tuberculosis. "A recent meta-analysis identified a significant association between an intron mutation of TLR9 and tuberculosis in humans." (PMID 25496717, 2014). "Tlr9 and Tlr2 double knockout mice display a more pronounced susceptibility to infection by tuberculosis than single gene knockout mice." (PMID 16608528, 2006). "Interestingly, the studies on experimental models of tuberculosis and patients with primary tuberculosis also indicate that a defect in TLR9 signalling predisposes them to the disease." (PMID 30218032, 2018). "Moreover, a correlation was seen between susceptibility to tuberculosis and the T/T genotype at the 2340 C > T locus in the TLR9 gene (P = 0.030, OR = 3.31, 95% CI = 1.05-10.40)." (PMID 25496717, 2014). "The TLR9 agonist CpG ODN increased IFN-γ responses in whole blood of tuberculosis patients using our in-house assays (6,768 ± 21,097 mlU/ml vs. 2,971 ± 4,780 mlU/ml, p = 0.31), yet not significantly." (PMID 39920589, 2025). "Different single nucleotide polymorphisms of TLR8 and TLR9 confer varying degrees of risk in the development of tuberculosis, suggesting that TLR8 and TLR9 are involved in tuberculosis." (PMID 35309296, 2022). "Previous studies indicated that the single nucleotide polymorphisms (SNPs) in TLR9 gene might be associated with Tuberculosis (TB) risk." (PMID 25948535, 2015). "Among the TLR family, TLR2, TLR4, and TLR9 and their adaptor molecule MyD88 play the most prominent roles in the initiation of the immune response against tuberculosis." (PMID 21603213, 2011). "Finally, four haplotypes were observed in the TLR9 gene, none of which displayed a significant association with resistance/susceptibility to tuberculosis." (PMID 25496717, 2014). "The table summarizes the mean percentages of inflammatory cells expressing TLR1, TLR2, TLR4, TLR7, and TLR9 in LNs from patients with AOSD, tuberculosis (Tb) lymphadenitis, T cell lymphoma, histiocytic necrotizing lymphadenitis (HNL), and reactive LNs." (PMID 35715478, 2022). "Distinct genetic loci may also play a role in the observed spectrum of M. tuberculosis infection phenotypes in humans with recent candidate gene case–control studies identifying polymorphisms in IL10 and TLR9 associated with latent TB but not active TB." (PMID 28646863, 2017).
anemia (15 papers, 2017 to 2025). A reduction in the number of red blood cells, the amount of hemoglobin, and/or the volume of packed red blood cells. "RBCs bind excess CpG DNA via toll-like receptor 9 (TLR9), leading to morphological changes and erythrophagocytosis by macrophages, causing anemia and systemic inflammation." (PMID 39234544, 2024). "Recently, studies have shown that mtDNA/TLR9 ligation is linked to anemia development during inflammation." (PMID 36835307, 2023). "The anemia, blood monocytosis, and splenic neutrophilia of Pld4thss/thss mice were also TLR9 dependent and shared with PLD4-deficient mice on the B6 background." (PMID 37555846, 2023). "Though a result of multiple causes, anemia can also be driven by chronic TLR-7 and TLR-9 signaling, initiating the differentiation of inflammatory hemophagocytes." (PMID 37508529, 2023). "In one study, IFN-γ knockout abrogated the development of anemia in a murine model of toll-like receptor 9 (TLR9)-induced fulminant macrophage activating syndrome." (PMID 36387094, 2022). "This binding activates the TLR9 response, resulting in accelerated erythrophagocytosis, and thus, the development of anemia." (PMID 35734577, 2022). "To determine the in vivo relevance of T-bet+ B cells in malarial anaemia, we infected Ifngr1−/−, Tbx21−/− and Tlr9−/− mice with P. yoelii and followed the levels of splenic CD11c+ T-bet+ B cells, anti-PS IgG antibodies and the development of anaemia." (PMID 29101363, 2017). "Furthermore, the enhanced chronic Toll-like receptor 9 signaling in SSc may also contribute to anemia via the differentiation of dysfunctional hemophagocytes." (PMID 36078943, 2022). "Hemophagocytosis is reported in this model of MAS where splenic hemophagocytosis was observed following blocking of IL-10 and the role of IFN-γ to mediate anemia was shown to be not necessary for fulminant TLR-9–induced MAS and hemophagocytosis." (PMID 38558807, 2024).
Hepatitis (15 papers, 2012 to 2026). Inflammation of the liver. "The CITE-seq data predicted a type I and II IFN signature in multiple hepatic leukocyte populations associated with TLR9-induced liver inflammation." (PMID 41561071, 2026). "In summary, we show that type I and II IFN-induced STAT1 activation drives TLR9-associated features, particularly liver inflammation, which is characterized by IFN-γ-producing cycling T cells, cDC2s, and monocytes transitioning into inflammatory Mφs." (PMID 41561071, 2026). "TLR9 A1486G carriers have been found to be associated with a decreased risk of Acinetobacter baumannii in a Chinese population, and the C2848T polymorphism is significantly positively related to neonatal severe hepatitis among Chinese newborns." (PMID 33777838, 2021). "Endolysosomal exonucleases, phospholipase D3 (PLD3), and PLD4 (type II transmembrane proteins) degrade TLR9, and their genetic deficiency causes an enhanced TLR9 expression and TLR9-dependent severe inflammation (lethal hepatitis), causing the death of newborns within two to three weeks after birth." (PMID 33643304, 2020). "With our ex vivo digestion protocol, we found that liver-resident KCs are depleted during TLR9-induced liver inflammation." (PMID 41561071, 2026). "Overall, our analysis suggests that type I and II IFN-induced activation of STAT1 is driving the expansion of inflammatory transitioning monocytes during TLR9-induced liver inflammation." (PMID 41561071, 2026). "IFN-γ blockade has been shown to be effective in the repeated TLR-9 model, while monomethyl fumarate, which upregulates IL-10 production via HO-1, ameliorates cytopenia and hepatitis." (PMID 36964620, 2023). "The role of TLR9 has been demonstrated in murine models with TLR9-knockout mice showing less fibrosis (and less severe hepatitis) than wild type mice." (PMID 24830559, 2014). "We propose that TLR9 stimulation, 24 hrs after T cell transfer, triggered a bystander hepatitis by first inducing INF-γ secretion in the liver." (PMID 23110209, 2012). "For example, the expression of TLR9 on transmembrane in mutant mice called TLR9TM in their early life proved detrimental (they suffer severe or lethal hepatitis and pancreatitis, systemic inflammation, and anemia), whereas the same mutation later in life induced only mild inflammation." (PMID 33643304, 2020). "The TLR9 activation on Kupffer cells leading to inflammation and activation of TLR9 on T cells, NK T cells, neutrophils, and sinusoidal endothelial cells also results in the secretion of pro-inflammatory cytokines in various liver inflammation models." (PMID 24340043, 2013). "The reduced expression levels of TLR2, TLR4 and TLR9 mRNAs or proteins can enhance protection against T cell-mediated hepatitis in mice, and the reduced expressions of TLR4, MyD88 and NF-κB may mediate the protective effects against LPS through reducing the level of pro-inflammatory cytokines." (PMID 30909396, 2019). "The bystander hepatitis induced by TLR3 and TLR9 stimulation produced a steady increase in the expression of VCAM-1." (PMID 23110209, 2012). "Although the anti-TLR9 mAb ameliorates TLR9-dependent lethal hepatitis, we did not identify any healing effect in NZBWF1 mice." (PMID 34868046, 2021). "However, mice treated with both a TLR9 agonist and IFN-γ reproduced the main features of HLH, developing cytopenias, hepatitis, and hepatosplenomegaly." (PMID 33802085, 2021). "When IL-10 signalling was maintained, the administration of the TLR9 agonist resulted in a milder HLH in wild-type (WT) mice, with less severe hepatitis and lack of hemophagocytosis." (PMID 33802085, 2021).
preeclampsia (15 papers, 2015 to 2025). Preeclampsia is a hypertensive disorder of pregnancy that is characterized by new-onset hypertension with proteinuria presenting after 20 weeks of gestation, and depending on mild or severe forms may initially present with severe headache, visual disturbances, and hyperreflexia. "In pregnancy, high levels of cell death are associated with preeclampsia through a mechanism involving mtDNA and TLR9 Also, high mtDNA levels in non-alcoholic steatohepatitis patients are reported to activate TLR9 and exacerbate the inflammatory profile." (PMID 31225514, 2019). "Using a mouse model of pre-term birth and preeclampsia, high levels of cff-DNA stimulated TLR9 to initiate acute inflammation, which caused fetal reabsorption at days 10–14, and knocking out TLR9 diminished this result." (PMID 26379664, 2015). "Interestingly, alterations in TLR9 signaling resulting from single nucleotide polymorphisms or the activation of this receptor via mtDNA have been linked to obstetrical pathologies such as preeclampsia and spontaneous preterm birth." (PMID 37149573, 2023). "In preeclampsia, dendritic cell TLR9 expression levels were higher, and upon stimulation, these receptors evoked more proinflammatory cytokines compared to healthy pregnant controls." (PMID 34831277, 2021). "Preeclampsia is marked by the release of cf-mtDNA and TLR9 activation, but other TLRs are attributed to this disease as well." (PMID 34831277, 2021). "Applying these findings to a mouse model, a TLR9 agonist induced the traditional hallmarks of preeclampsia and also reproduced the downregulated VEGFA and elevated sFLT-1 observed in human tissue." (PMID 34831277, 2021). "Increased expression of TLR9 in the placentae and peripheral blood mononuclear cells from women with preeclampsia compared to normotensive controls has also been described." (PMID 33013837, 2020). "This preeclampsia murine model also showed that with exogenous overexpression of TLR9, the levels of sFlt-1 increased while VEGF was downregulated." (PMID 33013837, 2020). "We showed TLR9 activity is significantly increased in women with preeclampsia compared to healthy controls at time of disease." (PMID 30976066, 2019). "There was a significant increase in TLR9 activity at TOD in preeclampsia cases compared to controls (0.29 ± 0.01 v 0.35 ± 0.01; P = 0.01)." (PMID 30976066, 2019). "Here we provide evidence that TLR9 activity is significantly increased at time of disease in women with preeclampsia." (PMID 30976066, 2019). "The aim of this study was to investigate if the increase in mtDNA we previously reported in preeclampsia triggers activation of TLR9 signalling cascade." (PMID 30976066, 2019). "We show that the activity of TLR9, a receptor for mtDNA, is significantly increased at time of disease in preeclampsia." (PMID 30976066, 2019). "We have shown a significant increase in TLR9 activity using a reporter cell assay incubated with plasma taken at time of disease in preeclampsia cases compared to healthy controls." (PMID 30976066, 2019). "We also reported a significant increase in endothelial TLR-9 gene expression with a consequent increase in pro-inflammatory cytokine TNF-α gene expression respectively in HUVEC treated with preeclampsia plasma." (PMID 27604418, 2016). "The Toll-like receptor 9 (TLR9) pathway plays a central role: as the key receptor for unmethylated CpG DNA motifs, TLR9 demonstrates significantly upregulated expression in placental tissue and peripheral blood monocytes from preeclampsia patients." (PMID 41048968, 2025). "This research supports a potential role of TLR9 activation of an innate immune response evident in preeclampsia which may possibly be initially triggered by dysfunctional mitochondria." (PMID 30976066, 2019). "This current study shows that the TLR9 activation of the innate immune system may play a role in the pathophysiology of preeclampsia in late gestation." (PMID 30976066, 2019).
preeclampsia (continued). "This indicates that the increase in mitochondrial DAMP (mtDNA) at time of disease may activate a TLR9 mediated innate immune response in preeclampsia cases only." (PMID 30976066, 2019). "In cases complicated with preeclampsia, both TLR9 and calprotectin were significantly increased across gestation (0.28 ± 0.02, 0.30 ± 0.02, 0.37 ± 0.02; P = 0.01) and (1318.69 ng/ml ± 87.95, 1233.77 ng/ml ± 68.45, 1946.55 ng/ml ± 145.84; P = 0.0001) respectively." (PMID 30976066, 2019). "Subsequently, preeclampsia plasma mediators significantly increased enodthelial TLR-9 gene expression (1.43 ± 0.17 fold, n = 8, P < 0.01) and pro-inflammatory TNF-α gene expression (2.65 ± 0.17 fold, n = 8, P < 0.01) in HUVEC respectively, compared to uncomplicated pregnancy." (PMID 27604418, 2016). "The TLR4 and TLR9 activation in adipose tissue may worsen the situation of patients with preeclampsia." (PMID 26089598, 2015). "Exaggerated placental cell injury and death result in the release of mitochondrial DNA, which activates TLR9 to produce systemic maternal inflammation from adipocytes, and subsequent vascular dysfunction that may in turn lead to preeclampsia." (PMID 26089598, 2015). "Finally, we have shown that possible activation of TLR-9 by dysfunctional mitochondria may provoke an exaggerated neutrophil-mediated innate immune response in preeclampsia." (PMID 30976066, 2019). "In this model, they hypothesized that TLR9 activation could cause preeclampsia; however, the different types of DNA were not able to induce preeclampsia-like symptoms." (PMID 29269517, 2018). "The prevention of TLR-9 signalling may be one mechanism by which anti-malarial drugs, such as chloroquine and hydroxychloroquine, could possibly exert their beneficial effects in women with preeclampsia or aPL66,67." (PMID 29185455, 2017). "Therefore, the presence of nuclear DNA in placental EVs, which are derived from trophoblasts, may also contribute to TLR-9 activation and endothelial cell dysfunction observed in preeclampsia." (PMID 29185455, 2017). "It is noteworthy that TLR9 has been reported to inhibit angiogenesis by downregulating VEGFA and upregulating sFLT1 in placentas from an animal model of preeclampsia and in trophoblasts." (PMID 34828331, 2021). "There is evidence of increased TLR9 expression in both placental tissue and peripheral blood mononuclear cells (PBMC) from patients with preeclampsia compared with controls." (PMID 30976066, 2019). "However, in preeclampsia, significant increases were seen in neutrophil activation markers, TLR9 and calprotectin, illustrating that the innate immune response may be initially triggered earlier in preeclampsia but complete activation is not significantly evident until later in pregnancy." (PMID 30976066, 2019). "Real-time PCR analysis showed increased expression of inflammatory markers TNF-α, TLR-9 and ICAM-1 respectively in endothelial cells treated with preeclampsia plasma." (PMID 27604418, 2016). "TLR9 has been shown to correlate with the inhibition of angiogenesis by downregulating the vascular endothelial growth factor (VEGF) and upregulating the soluble VEGF receptor 1 (sVEGFR1, sFLT1) at the fetomaternal interface with preeclampsia." (PMID 34828331, 2021). "RT-qPCR confirmed aberrant expression of genes involved in inflammation and stress response (TLR4 and TLR9) and also genes involved in host defense (PRDX5, MIF, CD74, NFE2L1, and CSF3R), suggesting that preeclampsia sera suppress the TLR4/9-dependent excess oxidative stress in adipose tissue." (PMID 26089598, 2015). "This study showed that preeclampsia sera stimulate expression of TLR4 and TLR9 in adipose tissue." (PMID 26089598, 2015).